HMGB1 (high mobility group box 1)
Diseases named in the same sentence as HMGB1 in open-access papers (continued):
Sharing a sentence is not in itself a finding about the gene and the disease.
diabetes (continued). "In the present study, we demonstrated that, similar to diabetes, HMGB1 caused a significant decrease in the synaptic vesicle protein synaptophysin and a significant increase in the activated cleaved caspase-3 in the retina of normal rats." (PMID 23766563, 2013). "In the present study, we reported that increased hyperlipidemia was associated with increased DAMP factor HMGB1 and inflammation in diabetic muscle myopathy, which could be a triggering agent in increased pyroptosis in diabetes." (PMID 36829889, 2023). "HMGB1 and autophagy are closely linked to diabetes and its complications." (PMID 37065747, 2023). "Studies have shown that the release of HMGB1 may cause necrosis in islet β cells induced by IL-1β and may lead to diabetes onset." (PMID 37065747, 2023). "HMGB1 and autophagy are closely associated with diabetes and its complications." (PMID 37065747, 2023). "Neuropathic pain, resultant from nerve damage or diabetes, is similarly associated with translocation of HMGB1 in dorsal root ganglia sensory neurons where it becomes available for signaling at neighboring neurons, glia and resident cells within the sensory ganglia and surrounding nerve." (PMID 34621188, 2021). "Our results demonstrated that PKC/HMGB1/RAGE/NF-κB signaling may participate in diabetes-associated impairment of oral wound healing." (PMID 34573077, 2021). "In addition, HMGB1 is linked to some diseases characterized by cell damage and death such as diabetes and Alzheimer's disease." (PMID 33384585, 2020). "Thus, an increase of HMGB1 has been linked to many inflammatory diseases such as allergic asthma, diabetes, atherosclerosis and heart failure." (PMID 28630596, 2017). "In addition, an associations between level of HMGB-1 and clinical complications of diabetes has been reported." (PMID 28789654, 2017). "In addition, the underlying mechanism by which diabetes induces HMGB-1 was investigated in this study." (PMID 26798412, 2016). "Finally, HMGB-1-induced insulin deficiency and insulin resistance contribute to the development of diabetes." (PMID 27847406, 2016). "HMGB-1 was shown to be increased at the onset of cystic fibrosis-related diabetes and was associated with indexes of glucose metabolism and body mass index in diabetes; however, treatment with insulin lowered its levels induced by glucose infusion." (PMID 27847406, 2016). "Associations of circulating HMGB1 levels with diabetes in full adjusted models." (PMID 26317615, 2015). "Next, we asked the question whether HMGB-1 affects endothelial cell activity, since it is changed significantly in the diabetic retina and associated with increased blood retinal permeability." (PMID 24498140, 2014). "HMGB1 has been linked not only to diabetes and CVD, but also to inflammatory diseases and cancer, which may explain the stronger association with all-cause mortality than with CVD observed in the present study." (PMID 22752054, 2012). "Diabetic nephropathy (DN), a severe complication of diabetes and a leading cause of end-stage renal disease, is strongly associated with chronic inflammation triggered by damage-associated molecular patterns (DAMPs), such as high-mobility group box 1 (HMGB1), S100A8, and S100A9." (PMID 41367913, 2025). "Notably, HMGB-1 has been associated with numerous inflammatory diseases, including cancer, trauma, arthritis, ischemia-reperfusion injury, sepsis, cardiovascular shock, diabetes, and autoimmune diseases." (PMID 39271468, 2024). "In addition, some have suggested that diabetes may represent a form of sterile inflammation, leading to activation of high mobility group box 1 (HMGB1), a damage associated molecular pattern (DAMP) (Tsung, Tohme, and Billiar 2014, Andersson and Tracey 2011)." (PMID 31269685, 2019). "In conclusion, our study demonstrates that topical application of rTMD1 enhances corneal wound healing in diabetes by inhibiting HMGB1/TLR4/NLRP3/IL‐1β–mediated inflammation." (PMID 41503166, 2026).
diabetes (continued). "A similar mechanism operates in diabetes mellitus, where HMGB1 contributes to disease progression by activating the TLR4/endothelial nitric oxide synthase signaling pathway." (PMID 40362460, 2025). "We envisage this review shall be more instrumental in persuading more studies towards exploring HMGB-1 suppression and antagonism in the delaying the onset and progression of diabetes complications." (PMID 39271468, 2024). "Mounting evidence suggests that HMGB-1 plays a crucial role in both the initiation and progression of diabetes." (PMID 39271468, 2024). "There is a functional link between SIRT1, with anti-inflammatory properties, and HMGB1 in the regulation of BRB breakdown induced by diabetes." (PMID 38716357, 2024). "Elevated levels of HMGB-1 have been detected in the serum, islets, and other tissues such as adipose, liver, and muscle in individuals with diabetes and animal models." (PMID 39271468, 2024). "Remarkably, high HMGB1 levels were detected in the serum and tissues of patients with atherosclerosis-related diseases, such as diabetes, ischemic stroke, and hypertension." (PMID 39596269, 2024). "Given the parallels between inflammatory responses and type 2 diabetes (T2D) development, this review paper explores HMGB-1’s potential involvement in onset and progression of diabetes complications." (PMID 39271468, 2024). "In this context, HMGB1 downregulation has been reported to correlate with suppressed apoptosis and enhanced autophagy in experimental models of cardiotoxicity, diabetes, and testicular damage." (PMID 38931349, 2024). "Ongoing and future projects in this realm hold promise for innovative approaches targeting HMGB-1-mediated inflammation to ameliorate diabetes and its complications." (PMID 39271468, 2024). "On the basis of this evidence, we explored the association between HMGB1 and DKD in a population with diabetes." (PMID 38481996, 2024). "Next, we found that the levels of HMGB1 in serum and urine are related to age, duration of diabetes, the proportion of hypertension and CVD." (PMID 38481996, 2024). "The diabetes + saline treatment group had significantly higher levels of HMGB-1 in the sciatic nerve (9.2 ± 0.1 pg/mg)compared to the control group (4.01 ± 0.07 pg/mg) (p < 0.001)." (PMID 38055406, 2023). "Mechanistically, NK regulated diabetes‐induced inflammation partially by modulating HMGB1 signaling in the activated microglia." (PMID 37403338, 2023). "GA, an inhibitor of HMGB1, reduces endothelium-dependent relaxation impairment by upregulating eNOS expression in an animal model of diabetes, and it attenuates neointimal formation in a rat model of iliac artery balloon injury." (PMID 37266147, 2023). "High levels of HMGB1 are expressed in obesity and diabetes pathological conditions, and the protein is directly correlated with body mass index." (PMID 36901121, 2023). "In recent years, studies on the treatment of diabetes and its complications by modulating HMGB1 with traditional Chinese medicine (TCM) are increasing and becoming a research hotspot." (PMID 37065747, 2023). "Englazine, GLP-1Ras, and DPP-4is have been shown to regulate HMGB1 and autophagy and play a role in the treatment of diabetes." (PMID 37065747, 2023). "In this article, we have summarized the relationship between autophagy and HMGB1 in diabetes and its complications and discussed potential therapeutic strategies to alleviate diabetes by regulating autophagy and HMGB1." (PMID 37065747, 2023). "MiR-126 was reduced in the aorta of ApoE −/− mice with diabetes, which induced ROS production and endothelial inflammation by enhancing the expression of high-mobility group box 1 (HMGB1)." (PMID 37660030, 2023). "Meanwhile, we found that ingredients and compounds in traditional Chinese medicine (TCM) can treat diabetes by regulating HMGB1 and autophagy." (PMID 37065747, 2023).
diabetes (continued). "HMGB1 and TLRs are reported to be upregulated in several autoimmune diseases, such as rheumatoid arthritis, systemic lupus erythematosus, type 1 diabetes mellitus, and autoimmune thyroid disease." (PMID 37667233, 2023). "Senescent cells can directly cause insulin resistance and aggravate the burden of diabetes through SASP containing MCP-1, insulin-like growth factor binding protein 3 (IGFBP-3), high mobility group box 1 (HMGB-1), IL-6, and PAI-1." (PMID 37511296, 2023). "Although some studies have been conducted on the role of autophagy and HMGB1 in diabetes and its complications, the pathological mechanisms of autophagy dysfunction, abnormal HMGB1 expression, and induced injury remain largely unexplored." (PMID 37065747, 2023). "In this paper, we review recent advances in the role of HMGB1 and autophagy in diabetes and its complications, providing new ideas for the treatment and research of this disease." (PMID 37065747, 2023). "Further, HMGB1 expression has been shown to be inhibited by metformin, a medication with anti-inflammatory properties commonly used to manage diabetes." (PMID 36982926, 2023). "In this review, we will introduce the biological and structural characteristics of HMGB1 and summarize the existing knowledge on the relationship between HMGB1, autophagy, diabetes, and diabetic complications." (PMID 37065747, 2023). "Continuous intake of glycyrrhizin acid after the onset of diabetes significantly downregulates retinal HMGB1 expression." (PMID 37667233, 2023). "Diabetes is also characterized by inflammation, as well as increased serum levels of high-mobility group box 1 (HMGB1) protein, an endogenous protein reported to activate toll-like receptors (TLRs), such as TLR2 and TLR4." (PMID 36674890, 2023). "To examine the effect of the hyperglycemia accompanying diabetes on the activation of TLR4 by HMGB1, we performed similar experiments in medium with high (4.5 g/L)—or normal (1 g/L)-glucose concentration." (PMID 36982926, 2023). "Conversely, Chung used englitazone to suppress HMGB1 expression, thereby impairing autophagy and disrupting cellular function, ultimately inducing diabetes." (PMID 37065747, 2023). "Diabetes led to an increase in HMGB1 tissue immunopositivity since strong/moderate HMGB1 immunopositivity is detectable in the cytoplasm of many hepatocytes." (PMID 36012572, 2022). "In the present study, we observed that Fer-1 treatment reduced diabetes-induced nuclear-to-cytoplasmic translocation of HMGB1, and it increased overall expression." (PMID 36012572, 2022). "Previous studies have revealed that HMGB1 inhibitor GA treatment protects against kidney lesions induced by diabetes, which is related to the reduced expression of TNF-α, 1L-6, IL-1β, MCP-1, and ICAM-1 in the kidney." (PMID 35578754, 2022). "Therapeutically, activated-PAK2 remediated ER function, and extracellular inhibition of HMGB1 represses ER stress-induced inflammation and subsequent dysfunction in diabetes." (PMID 35281739, 2022). "Taken together, these results reveal that hyperglycemia and hyperlipidemia induce cardiac-sourced HMGB1 upregulation and secretion in diabetes." (PMID 35281739, 2022). "For example, serum HMGB1 is a predictive biomarker of type 2 diabetes mellitus (T2DM) and chronic obstructive pulmonary disease (COPD)." (PMID 35706377, 2022). "We have recently shown that changes in oxidative state in diabetes induce redox modification of high-mobility group box 1 (HMGB1), an important driver of inflammation signaling." (PMID 36012572, 2022). "Vascular endothelial cell inflammation and dysfunction are common complications of diabetes that is controlled by hyperglycaemia‐induced miR‐106 and subsequent induction of HMGB1 expression and inflammation." (PMID 35706377, 2022). "We therefore obtained evidence of the interplay between cardiac HMGB1 and myocardial inflammatory reactions under diabetes." (PMID 35281739, 2022).
diabetes (continued). "The mechanism underlying the negative impact of chronic inflammation on neurodegeneration in diabetes is the reduction of neurotrophic factors and activation of caspase-3 by HMGB1-related proinflammatory cytokines, which is confirmed by Hmgb1 gene knockout." (PMID 35578754, 2022). "The diabetes-induced HMGB1 upregulation is primarily evoked by diabetic oxidative stress, which modulates its degree of activity and HMGB1 translocation from the nucleus to the cytoplasm or extracellular compartment." (PMID 33915770, 2021). "The diabetes-induced HMGB1 shuttling from the nucleus with subsequent activation was triggered mainly by the persistent hyperglycemia and the inflammatory agents, such as IL-1β and TNF-α." (PMID 33915770, 2021). "RSV significantly attenuated diabetes-induced downregulation of occludin and diabetes-induced upregulation of high-mobility group box-1 (HMGB1), as well as the receptor for advanced glycation end products and BRB breakdown in diabetic retina." (PMID 33525499, 2021). "In summary, AL can improve diabetes-induced cognitive dysfunction, and its mechanism is related to the regulation of hippocampal Nrf-2/HO-1/ HMGB1/NF-κB signaling pathway, and its in-depth mechanism needs further study." (PMID 34319254, 2021). "Diabetes, in particular, is known to exacerbate systemic inflammation as evidenced by “priming the lung” with higher serum high mobility group box 1 (HMGB1), higher cytokine levels and enhanced lung injury in a systemic inflammation animal model." (PMID 34375359, 2021). "HMGB1 increased in the submandibular gland of the diabetes-xerostomia rats model, and 8-OHdG increased in the saliva of xerostomia patients." (PMID 35056946, 2021). "Growing evidence illustrated that diabetes up‐regulated HMGB‐1 expressions in vascular cells, including endothelial cells and smooth muscle cells." (PMID 33724642, 2021). "Despite extensive studies concentrated on the role of HMGB‐1 in diabetic complications, there is little information regarding the relationship between HMGB‐1 and vascular calcification in diabetes." (PMID 33724642, 2021). "HMGB-1, S100, IL-33 are only some examples of how these danger signals are important in the etiopathogenesis of pathologies like heart failure, obesity, diabetes, hypertension." (PMID 34042528, 2021). "As a key mediator of oxidative stress and inflammation, the role of the high mobility group box-1 (HMGB-1), a representative damage-associated molecular pattern (DAMP), in diabetes is gaining increasing attention." (PMID 34573077, 2021). "This is also actually a very important omission of the model that was detected by an expert human (the reviewer), because expression of HMGB1 is enhanced by hyperglycemia, in conditions such as obesity, systemic inflammation and diabetes." (PMID 34395368, 2021). "It has been previously proved that NLRP3 inflammasome-mediated HMGB1 release plays a vital role in endothelial hyperpermeability during several metabolic disorders such as obesity, hyperglycemia, and diabetes." (PMID 34838052, 2021). "Clinical studies demonstrated that serum HMGB‐1 level was increased in both of type 123 and type 224, 25 diabetes mellitus, which reflected pro‐inflammatory state of diabetes." (PMID 33724642, 2021). "HMGB1 expression is reportedly increased in the spinal cord in diabetic neuropathic pain and mechanical compression pain, in which anti-HMGB1 neutralizing antibodies reverse the pain-related behavior in rodents." (PMID 34794382, 2021). "Herein, in vitro and in vivo experiments were performed to detect the role of ERS in diabetes‐induced HMGB‐1 secretion." (PMID 33724642, 2021). "As in vivo experiment showed that inhibition of HMGB‐1 or ERS prevented diabetes‐induced vascular calcification, in vitro experiments on VSMCs were performed to confirm the roles of HMGB‐1 and ERS in vascular calcification." (PMID 33724642, 2021).
diabetes (continued). "Collectively, these data demonstrate that blockade of HMGB1 during early beta cell mass turnover prevented insulitis progression and, as a result, decreased the incidence of diabetes in NOD mice." (PMID 32072192, 2020). "Treatment with LPLI significantly decreased diabetes-induced high mobility group box 1 (HMGB1) and tumor necrosis factor alpha (TNF-α) expression, while enhancing the activation of the transcriptional factor cAMP response element binding (CREB) protein." (PMID 32750068, 2020). "Neutralising HMGB1 both delayed diabetes onset and, of particular relevance, reversed diabetes in 13 out of 20 new-onset diabetic NOD mice." (PMID 32072192, 2020). "As expected, diabetes significantly increased inflammatory markers such as, HMGB1 and TNF-α in SMG, as well as the receptor RAGE with a tendency of increase in the activation of the transcriptional factor NFκB." (PMID 32750068, 2020). "Our initial results showed that blockade of HMGB1 was highly effective in reversing diabetes, as evidenced by inducing long-term normoglycaemia (>120 days)." (PMID 32072192, 2020). "In line with our mouse data, individuals with diabetes manifested significantly higher levels of circulating HMGB1 than control participants." (PMID 32072192, 2020). "Blockade of extracellular HMGB1 altered the course of the disease even after the autoimmune response had evolved into overt diabetes." (PMID 32072192, 2020). "The early retinal neuropathy induced by diabetes is, at least in part, attributable to the diabetes-induced upregulation of HMGB1." (PMID 32722545, 2020). "Inhibiting the release of HMGB1 with a constant intake of GA results in the reduction of diabetes-induced retinal neuropathy." (PMID 32722545, 2020). "As expected, blockade of HMGB1 remarkably reduced diabetes incidence (84.6% vs 60%) and delayed diabetes onset (16.7 ± 0.8 vs 19.6 ± 1.1 weeks)." (PMID 32072192, 2020). "Together, our results support that neutralising HMGB1 reversed new-onset diabetes, decreased insulitis and preserved insulin-staining islets in diabetic NOD mice." (PMID 32072192, 2020). "Intravitreal injection of HMGB1 mimics the effects of diabetes and increases RAGE, ERK1/2, NF-κB, and proinflammatory biomarkers such as ICAM-1 and soluble ICAM-1." (PMID 32722545, 2020). "Once diagnosed with diabetes, the mice were treated with either the anti-HMGB1 (500 μg/mouse) or mouse IgG every other day for two weeks." (PMID 32072192, 2020). "Inhibition of extracellular HMGB1 in experimental models of myocardial ischemia/reperfusion injury, myocarditis, cardiomyopathies induced by mechanical stress, diabetes, bacterial infection or chemotherapeutic drugs reduces inflammation and is protective." (PMID 30306212, 2019). "It is noteworthy that most animal models of dilated cardiomyopathy are related to a specific cause such as MI, aortic constriction, anthracyclines, myocarditis, and diabetes; the role of HMGB1 in these conditions has been addressed above." (PMID 30306212, 2019). "In diabetes condition, hyperglycemia promotes directly or indirectly, through ROS and AGEs production, the release of HMGB1." (PMID 31835864, 2019). "Additional research into the effectiveness of P. cuspidatum indicated that it controls RAGE-mediated activation of NF-κB, followed by inhibition of upregulation of HMGB1 and prevention of diabetes-induced retinal vascular hyperpermeability." (PMID 29937497, 2018). "The binding of TLR4 and CXCR4 to HMGB1 is crucial to trigger chronic inflammation response in diabetes." (PMID 30647535, 2018). "Both TLR4 and CXCR4 are G protein-coupled receptors and can bind to the HMGB1 in cytoplasm, which expression level is elevated in diabetes." (PMID 30647535, 2018). "When NOD mice were treated with HMGB1 neutralizing antibody, the insulitis progression was significantly inhibited and the diabetes incidence was also decreased." (PMID 30410469, 2018).